CD68 (CD68 molecule)
Diseases named in the same sentence as CD68 in open-access papers (continued):
Sharing a sentence is not in itself a finding about the gene and the disease.
tumor (continued). "The TMA1 cohort of Zhongshan Hospital was used for mIF staining to examine the expression of NUPR1 and CD68 in tumor tissues compared to adjacent tissues." (PMID 40305758, 2025). "Strikingly, the tumor T2* values positively correlated with the CD68+ (r=-0.68, P = 0.031) and CD163+ (r=-0.76; P = 0.010) TAM quantities, as observed by histopathology." (PMID 39865337, 2025). "On-treatment tumours from the MOv18 IgE Phase I trial show evidence of this IgE-driven immune signature, with increased CD68+ and CD3+ cell infiltration." (PMID 40210642, 2025). "These tumours also express tumour‐associated genetic markers (e.g., CD44v6, CDX2, BRAF) and immune markers (e.g., CD68, CD163), alongside characteristics like CpG island methylator phenotype and KRAS mutations." (PMID 40444502, 2025). "Decreased ferritin expression in tumor cells but an increased infiltration of ferritin-rich CD68-positive macrophages was observed with increasing tumor histological grades." (PMID 39852175, 2025). "To evaluate TAM abundance across HNSCC, BC and CRC tumor samples, we developed a 4-plex mIF assay to detect CD68, CD163, PD-L1 and cytokeratin." (PMID 41415295, 2025). "The patient’s OS was unrelated to the total CD68+ TAMs in the tumor islet or stroma, which is intriguing." (PMID 40422244, 2025). "In this study, we showed that NRP1+ non-tumor cells identified in the TME of MB tissues correlate with CD68 expression, indicating high NRP1 expression in TAMs." (PMID 40805120, 2025). "Except for M09, all other subtypes expressed macrophage markers such as CD68, C1QB, S100A9, and AIF1, suggesting that they are tumor-associated macrophages (TAMs)." (PMID 40260248, 2025). "Tumor cell immunostaining for S100 protein, neuron-specific enolase, and CD68 confirms the schwannian nature of the tumor." (PMID 40726893, 2025). "Although NKp46+ NKT cells are abundant in the tumor region close to tumor cells, CD68+ macrophages are primarily found in the stroma." (PMID 40422244, 2025). "The expression of CD68 and CSF1 associated with tumor-associated macrophages (TAM) were significantly downregulated in NPRL2-treated samples." (PMID 39932765, 2025). "We discovered that ALDOA is not only highly expressed in tumor cells but is also remarkably enriched in CD68 + macrophages themselves." (PMID 41239433, 2025). "Tumor development was accompanied by significant fibrosis and infiltration with CD68-positive immune cells." (PMID 40490362, 2025). "CXCL17 promotes the infiltration of CD4+ T cells and CD68+ immune cells into the tumor microenvironment, thereby accelerating tumor growth and metastasis." (PMID 41459506, 2025). "Lastly, for CD68+ macrophages, the CD40LG_IHC_Score was weakly positively correlated only in the tumor region (r = 0.21, p = 0.0069)." (PMID 41048996, 2025). "Patients with a high infiltration level of CD68+ cells and Foxp3+ cells in tumor tissues are likely to benefit from neoadjuvant mono-immunotherapy." (PMID 39889711, 2025). "Among PD‐L1‐positive samples, 6% contained cells that expressed PD‐L1 only on the tumour cells (PD‐L1+/CK+), while 23% of the samples had cells that were PD‐L1+/CD68+ only." (PMID 40545725, 2025). "Studies across NMIBC and MIBC cohorts have shown a positive correlation between TAM numbers, identified by the pan-macrophage marker CD68, and both higher pathological T grades and advanced tumor stage." (PMID 40136652, 2025). "CD68 is an essential indicator for evaluating macrophage presence in the tumor microenvironment of DLBCL." (PMID 40599139, 2025). "Immunofluorescence staining revealed that the regions with IL7R-expressing tumor were specifically enriched with CD68+CD206+ macrophages." (PMID 41360767, 2025). "The results revealed a significant increase in the protein levels of CD163, CD14, and CD68 in the tumor tissue compared to adjacent tissue (p < 0.0001)." (PMID 40270962, 2025).
tumor (continued). "Distant metastasis (pM). ccRCCs with synchronous distant metastases exhibited significantly higher percentages of FAP + and CD68 + cells at the tumor periphery as well as elevated percentages of CD8 + and CD68 + cells at the tumor center." (PMID 39751643, 2025). "In terms of infiltrating immune cell distribution, CD20+ B cells, CD8+ T cells, CD4+ T cells, and CD4+ FoxP3+ Treg cells were mainly distributed in the stroma, whereas CD68+ macrophages were concentrated in the tumor parenchyma." (PMID 40710213, 2025). "Specifically, when tumor thickness was less than 1.0 mm (<0.8–1.0 mm), the average number of intratumoral CD68+ macrophages was 29.7 ± 4.3 cells, whereas at a thickness greater than 4.0 mm, this value increased to 70.3 ± 6.4 cells." (PMID 41007741, 2025). "We observed an infiltration of CD8- or CD68-positive immune cells in the current SCLC-transformed tumor." (PMID 41001033, 2025). "Both GLUT1 and P-Akt2 co-localized with 80% of the CD68-expressing macrophages within these tumor samples, suggesting a high degree of GLUT1 activation in pNF- and MPNST-associated macrophages." (PMID 40279245, 2025). "Analysis of TCGA‐OC cohort revealed a strong correlation between CMTM4 expression and CD68+ macrophage infiltration, which was further validated in both human and murine tumor samples." (PMID 40433989, 2025). "We used keratin expression (KRT7, KRT8, and KRT19) to visualize the tumor area and CD68 to mark myeloid cells." (PMID 40917508, 2025). "Tumor-infiltrating CD68+ pan-macrophages, CD163+ M2 like- macrophage, and CD8+ T cells were assessed using immunohistochemistry and immunofluorescence." (PMID 41573553, 2025). "Contrary to our results from the tumor samples, a low density of stromal CD68+CD163− macrophages in normal tissue samples was prognostically favorable (p = 0.050), while the opposite was true for CD68+ CD163+ (p = 0.004), where a high density was favorable." (PMID 40498004, 2025). "Conversely, the downregulation of CD68, a pan-macrophage marker, may reflect a reduced proportion of classically activated macrophages relative to M2-polarized subsets, thereby reinforcing the dominance of an immunosuppressive tumor-associated macrophage (TAM) phenotype." (PMID 41304988, 2025). "Overall, CD68+ cells were the most prevalent immune population at baseline and across all tumor treatments." (PMID 41514652, 2025). "Fractions of Rep+CD68+ MPs among all MPs were increased in tumor-distant (mean 27.0%) and peritumor (23.1%) tissues of CRC patients compared to tumor tissues (4.7%, p < 0.0001 and p < 0.01)." (PMID 40136704, 2025). "CD68 and CD163, for example, are tumor-associated macrophage (TAMs) markers, which recognizes M1 and M2 type macrophages." (PMID 39904885, 2025). "This also undermines the positive prognostic relevance of CD68+CD163+ macrophages in the stromal compartment of normal tissue surrounding the tumor." (PMID 40498004, 2025). "The CD68+ subset neighborhood enrichment analysis was notable for greater enrichment of CD68+ cluster 2 with tumor cells in the HIV– group." (PMID 40459946, 2025). "The pathological specimens were analyzed for programmed death ligand 1 (PD-L1), Glypican-3, CD3-tumour infiltrating lymphocyte, CD68 positive cells, CD34 positive microvessel density (MVD)." (PMID 40640280, 2025). "Among these, macrophages, marked by the expression of CD68, are central to phagocytosis, immune regulation, and tumor progression." (PMID 40918116, 2025). "Based on the IHC DAB and IF staining, we noted comparable levels of Rep and CD68 tissue staining in tumor-distant and peritumoral tissues." (PMID 40136704, 2025). "These increases were also seen in the tumor periphery, with all treatment tumors exhibiting elevated CD68+ levels compared to the IgG control (IgG vs. PD1: p = 0.0035; IgG vs. PD1 + RT: p = 0.00025, PD1 vs. PD1 + RT: p = 0.00021)." (PMID 41514652, 2025).
tumor (continued). "We employed immunostaining for CD3, CD4, CD8, Granzyme B (GzmB), FOXP3, CD163, and CD68 markers to quantitively analyze the STR patient’s tumor immune landscape both at baseline and during STR 10–12." (PMID 40594889, 2025). "TAMs can be divided into M1 type and M2 type.M1 type TAMs expresses CD68 and promotes the inflammatory response, which usually has an anti-tumour effect." (PMID 40636693, 2025). "CD68 expression was significantly higher in the tumor stroma of metastases compared to the corresponding primary tumors (p = 0.011), with this difference primarily driven by HR+/HER2- tumors (p = 0.016)." (PMID 40510346, 2025). "CD68+ infiltrating macrophages were predominantly recruited to the tumor core, whereas TMEM119+ resident macrophages (microglia) were mainly clustered in invasive islands." (PMID 39781357, 2025). "We likewise found a broad infiltration of CD68 expressing cells in the tumor stroma in the overall cohort, with significantly higher levels in metastases compared to corresponding primary tumors." (PMID 40510346, 2025). "Our findings on CD68+CD163+CD206+ M2-type macrophages suggest a potential relevance of these macrophages in the stromal compartment of tumor distant normal tissue (p = 0.171)." (PMID 40498004, 2025). "IMC provided further evidence of a distinct immune phenotype in the high-SMIM25 group, with significantly higher CD4 and CD68 expression in the stromal region compared to the tumor region (p < 0.05)." (PMID 41020815, 2025). "Immunohistochemical analysis of the tumor cells showed strong immunoreactivity for vimentin (++), CD31 (++), and ERG (++), with most tumor cells also positive for CD68 (++)." (PMID 40283372, 2025). "Comparative analysis of BCL2A1+macrophages from tumor and adjacent normal tissues revealed highly similar expression of macrophage marker genes (e.g., CD68, CD163)." (PMID 40707992, 2025). "Based on histological features and immunostaining for SYTO13, PanCK, CD3D, and CD68, we selected eight regions of interest (ROIs) and defined segments representing tumor cells (SCC_Tumor, PanCK+, n = 8) and the surrounding TME (SCC_TME, PanCK‐, n = 8)." (PMID 40776410, 2025). "Macrophages were further categorized into proinflammatory (CD206−MHCII+CD68+ M1-like) and tumor-promoting (CD206+MHCII−CD68+ M2-like) phenotypes based on the expression of MHC-II and CD206, respectively." (PMID 40588561, 2025). "Immunohistochemistry staining showed a significant presence of CD68+ macrophages infiltrating the tumor core, while only a few TMEM119+ microglia were found." (PMID 39781357, 2025). "CD27 showed coexpression with scattered vimentin + CAFs (arrow) and CD3 + T-cells (arrows) in the stroma, and with a moderate number of CD68 + TAMs in the stroma compartment and inside tumor nests (arrows)." (PMID 40205178, 2025). "scRNA-seq data showed that BCL2A1+macrophages in tumor and normal tissues had highly similar expression of macrophage marker genes (such as CD68 and CD163), indicating consistent fundamental macrophage characteristics." (PMID 40707992, 2025). "The results revealed that CD68+ macrophages were more likely to be present in surrounding tumor-surrounding tissues than in normal tissues." (PMID 41354740, 2025). "Fifteen (43%) tumors presented at least moderate densities of CD68+PD‐L1+ macrophages at the tumor center and 12 (43%) at the invasive margin, and seven tumors (20%) had low densities in both areas." (PMID 39783790, 2025). "In our cohort, CD27 expression was restricted to the TME, showing coexpression with vimentin + CAFs, CD3 + T-cells, and a moderate number of CD68 + TAMs in the stroma and tumor nests." (PMID 40205178, 2025). "In another study, TAM (CD68+) infiltration in LC tumors, including tumor-promoting M2 macrophages (CD163+) and lymphocytes (CD3+), was significantly reduced after RESV treatment." (PMID 40948874, 2025).
tumor (continued). "Immunohistochemical analysis demonstrated significant decrease in CD68+ macrophage density within the tumor stroma, suggesting targeted engagement and modulation of the tumor microenvironment by MDC-735." (PMID 39900573, 2025). "CD68 expression was positive in ATC, indicating tumor-associated macrophage infiltration, but a few cells were double-positive for PTX3 and CD68." (PMID 41373493, 2025). "Quantification of main cell subpopulations of more than 35,000 individual cells obtained from patients/controls in the cohort showed comparable levels of CK+ tumor cells and CD68+ TAMs between PWH and PWOH." (PMID 40459946, 2025). "We found that the intra-T/peri-T ratio of CD86+ cells was significantly lower in CD68+ (pan-macrophage marker) cells than CD20+ tumor B cells (0.4 ± 0.1 vs 1.4 ± 0.4, p = 3e-13)." (PMID 41415285, 2025). "Increased CD68+ macrophages within the TME have been associated with unfavorable prognoses in DLBCL, suggesting a potentially detrimental role in tumor progression." (PMID 40599139, 2025). "Tumors from rat IgE 26-treated animals showed significantly increased infiltration of CD68+ macrophages in tumor and necrotic areas and of CD3+ T cells in tumoral, stromal and necrotic areas, compared to tumors from PBS controls." (PMID 39934835, 2025). "Our single-cell and spatial transcriptomic analyses revealed that STX7 is predominantly expressed in monocyte-derived macrophages in HCC, with dynamic upregulation during differentiation and co-localization with CD14 and CD68 in tumor regions." (PMID 40999361, 2025). "Most studies have demonstrated that tumor cells express S-100, CD68, and Vimentin, whereas markers such as CK, Syn, CgA, Desmin, and pituitary hormones are typical negative, with the majority of cases also showing negativity for GFAP." (PMID 40860841, 2025). "The observed trend indicates that CAFs expressing FAP as well as CD68 + macrophages and tumor-infiltrating lymphocytes (TILs) (CD4, CD8, and CD4 + FOXP3 +) are more abundant in the more aggressive ccRCCs." (PMID 39751643, 2025). "Our results show a higher expression of CD68 in the tumor stroma of brain metastases, whereas CD86 and CD163 showed comparable levels in both locations." (PMID 40510346, 2025). "For immunohistochemistry to detect components of the tumor microenvironment, we analyzed the distributions of PD-L1, markers of tumor-associated fibroblasts (SMA), markers of TAMs (CD163 and CD68), in the tumor and adjacent normal tissue." (PMID 40416971, 2025). "The tumor-infiltrating GZMB+CD8+ T cells were spatially adjacent to CXCL9+CD68+ macrophages, which were positively correlated." (PMID 41321309, 2025). "Increased expression of CD163, CD68 and CD3 (p < 0.0001, p = 0.0015 and p = 0.0024 respectively) was associated with partial tumor resection (PR)." (PMID 41044688, 2025). "In vivo labelling with fluorescent-tagged antibodies (B220, CD3, CD8a, CD68) in tandem with confocal microscopy allows for the identification of specific cell types (B cells, T cells and macrophages) in the tumour microenvironment (TME)." (PMID 39880930, 2025). "Bcl-2 expression was significantly lower in the CD68+ macrophage compartment compared with the CD20+ tumor cell compartment, but was correlated with M1 (CD86+) macrophage infiltration." (PMID 41415285, 2025). "In general, very similar Rep and CD68 staining patterns were observed in tumor-distant and peritumor tissues." (PMID 40136704, 2025). "CD68+ macrophage infiltration was markedly increased in both Cryo and iCryo groups relative to controls, with the iCryo group showing a tumor-to-liver ratio of 6.00 ± 4.37 vs. 1.63 ± 0.84 in controls (p = 0.0004)." (PMID 41377976, 2025). "We have previously identified TMEM doorway macrophages by their direct contact with a tumor cell and blood vessel, expression of CD68, Tie2, and VEGF-A, and further characterized them as a CD206+/CD11b+/F4/80+/CD11c− population." (PMID 40646332, 2025).
tumor (continued). "High CD68 expression correlated with a lower Ann Arbor stage (P = 0.040) and tumor morphology (P = 0.010)." (PMID 40599139, 2025). "Initial immunohistochemical analysis revealed negativity for S-100, AE1/AE3, α-SMA, desmin, and CD34 but positivity for CD68, suggesting a presumptive diagnosis of a fibrohistiocytic tumor." (PMID 40491616, 2025). "The presence of intense M2 macrophage infiltration (CD68+ or CD163+) in the tumor stroma was a poor prognostic factor and correlated with shorter disease-free survival (DFS) and OS, although the opposite tendency was observed at TF." (PMID 40508145, 2025). "Together with additional in vitro data that determined an increase in T cells and CD68+ macrophages, our results demonstrate the therapeutic potential of our particle-inducing anti-tumor immune cells." (PMID 40083938, 2025). "TAMs exhibit functional plasticity, polarizing toward either a pro-inflammatory, antitumor phenotype (M1, CD68-positive) or an anti-inflammatory, tumor-promoting phenotype (M2, CD163-positive)." (PMID 41239536, 2025). "Here, the only trend we identified was that supratentorial tumours possessed more CD68+ cells than infratentorial tumours longitudinally (p < 0.01)." (PMID 39948623, 2025). "Future studies incorporating single-cell RNA sequencing and functional assays are warranted to elucidate the precise mechanisms of CD68-mediated tumor immunity." (PMID 40918116, 2025). "Crohn's‐like reaction, T‐cell proximity score, and CD68+/PD‐L1+ on the tumor center and invasive margin were independent prognostic immune factors." (PMID 39783790, 2025). "Higher density of TAMs (CD68+) has been observed in cases with higher clinical stage, larger tumor size, higher histological grade, and higher Ki-67 proliferative index." (PMID 41150099, 2025). "There was a consistent trend (but NS) of higher tumor MDCLR in unresponsive patients also when assessed in FFPE biopsies considering CD68+ for MDC and the sum of CD3+ (T lymphocytes) and CD20+ (B lymphocytes) for lymphocytes." (PMID 40097400, 2025). "First, we determined the optimal passage of primary tumour cells for co-culture by culturing from passage 0 (P0) to passage 6 (P6) and assessing immune marker expression (CD68, CD163, and TMEM119) via western blotting." (PMID 40420192, 2025). "For CD68 expression in primary tumors, a significant difference between the tumor nest and tumor stroma was observed exclusively in HER2+ tumors (p = 0.008)." (PMID 40510346, 2025). "At least, in this study, we found a positive correlation between the number of tumor infiltering-CD68 + macrophages and CCL2, a chemokine able to recruit monocytes/macrophages at the site of inflammation." (PMID 40064752, 2025). "We detected a significantly higher density of CD68+Stat1+ macrophages within a 50 μm proximity to panCK+ tumor cells in responders compared to non‐responders (P<0.05)." (PMID 40995650, 2025). "The anti-PD1 + RT tumor showed the largest increase in CD68+ cells (p = 0.011) but also the largest variability (SD = 2.329)." (PMID 41514652, 2025). "It influences the recruitment and activation of TAMs (marked by CD68) and contributes to an inflammatory microenvironment favoring tumor progression." (PMID 41259576, 2025). "CD68+ cells predominantly localized to peripheral tumor regions, while CD163+ cells formed diffuse clusters in central tumor zones and around peripheral vessels." (PMID 40843751, 2025). "A numerically higher ORR was observed in patients with high baseline tumor-infiltrating immune cell densities than in those with low immune cell densities, with a small difference for CD68+ cells." (PMID 39679910, 2025). "The rest of the tumor immune microenvironment was represented by CD68 positive macrophages (20%) and mast cells (10%)." (PMID 40075893, 2025). "In agreement, CD86+ cell count was significantly higher in the macrophage (CD68+) than in the tumor cell (CD20+) compartment (282.0 ± 63.4 vs 238.1 ± 64.3, p = 0.02)." (PMID 41415285, 2025).